SETD7 (SET domain containing 7, histone lysine methyltransferase)
Diseases named in the same sentence as SETD7 in open-access papers (continued):
Sharing a sentence is not in itself a finding about the gene and the disease.
tumor (continued). "Thereafter, it was unveiled that SETD7 had significant higher expression in LUAD tissues than paired non-tumor tissues, so did in LUAD cell lines than in 16HBE cells." (PMID 33372601, 2020). "As expected, in rescue experiments, silencing SETD7 or KLF4 abrogated the tumour‐suppressive phenotypes by depletion of METTL3." (PMID 32126149, 2020). "We demonstrated that SETD7 promoted tumor cell proliferation and prevented cell apoptosis and that SETD7 delicately maintained the redox homeostasis through regulating the levels of GSH/GSSG and ROS." (PMID 29212211, 2017). "SETD7 exhibited a markedly higher expression in HCC tumor tissues than in ANLTs, as determined by qRT-PCR." (PMID 27183310, 2016). "Furthermore, IHC analysis revealed a decreased proportion of Ki67-positive cells in SETD7-knockdown tumors and an elevated Ki67 index in SETD7-overexpressing tumors, confirming that SETD7 promotes tumor cell proliferation in vivo." (PMID 41203594, 2025). "Conversely, SETD7 overexpression markedly increased tumor volume and weight." (PMID 41203594, 2025). "Moreover, SETD7 deletion decreased the growth rate of NCI-N87 cells in vivo, and IHC confirmed that SETD7-depleted NCI-N87 tumour masses manifested significantly weaker Ki-67 staining than the tumour masses derived from the control cells." (PMID 38670954, 2024). "Finally, metabolomic study of tumor tissues showed rewiring of metabolomic pathways and downregulation of amino acids, such as arginine, serine, and glycine) in Setd7 KO and WT treated with CPH compared to untreated Setd7 WT mice." (PMID 39522095, 2024). "Overall, these results imply a tumor-promotive effect of SETD7 in OC." (PMID 39725038, 2024). "Therefore, it is urgent and necessary to explore the potential novel substrates and methylation sites of SETD7, which is helpful to clarify the molecular mechanism of tumor progression and develop new therapeutic targets." (PMID 38904013, 2024). "Because SETD7 can positively or negatively regulate multiple proteins, its role in tumor progression may vary depending on the substrate and the cellular context." (PMID 39725038, 2024). "In addition, the diminished weight and number of metastatic tumours compared with those of the control group of intraperitoneal implant metastasis experiments proved that downregulated SETD7 inhibited the metastasis of HGC-27 cells in vivo." (PMID 38670954, 2024). "Furthermore, we utilized metabolomic analysis of in vivo tumor tissues to explore the intricate relationship between Setd7 and its inhibitor CPH with lung metastasis." (PMID 39522095, 2024). "For this reason, SETD7 can both activate and inhibit tumor-survival signals." (PMID 37055532, 2023). "Multiple reports have indicated that SETD7 exhibits tumor-suppressive functions." (PMID 38036730, 2023). "SETD7 was found to either stimulate or inhibit cell proliferation, survival, invasion or metastasis; these processes were grouped as tumour-promoting or tumour-suppressing for analysis purposes." (PMID 35326563, 2022). "Importantly, the functional studies showed that the tumour-suppression role of SETD7 is related to its methylation of oncogenic target proteins (Dnmt1, E2F-1 and HIF-1α) leading to their degradation." (PMID 35326563, 2022). "Therefore, SETD7 mRNA is downregulated by hMETTL3/DF2 m6A to increase the metastatic potential of BlaCa cells, which supports a tumour-suppressing function of SETD7." (PMID 35326563, 2022). "Two studies presented evidence of SETD7 as a tumour promoter." (PMID 35326563, 2022). "The role of SETD7 as a tumour promoter was reported by four studies." (PMID 35326563, 2022). "This usually corresponds to a better prognosis in the basal-like subtype, and thus suggests that the tumours expressing high SETD7 might benefit from immunotherapy." (PMID 36551516, 2022). "The tumour-suppressor role of SETD7 was reported by four studies." (PMID 35326563, 2022).
tumor (continued). "The results pointing towards a tumour-promoting role of SETD7 come from seven studies." (PMID 35326563, 2022). "Together, these results demonstrate that SETD7 may act as tumour suppressor by negatively modulating HIF-1α-, but this negative regulation may be impaired if LSD1 is also highly expressed/active." (PMID 35326563, 2022). "Studies supporting a tumour-suppressor role of SETD7 include four papers." (PMID 35326563, 2022). "In summary, under stress conditions, SETD7 may act as a tumour promoter reducing the response to therapy of LCa cells, since all studies except one found that downregulation of SETD7 or the inhibition of its activity increases sensitivity to chemotherapy." (PMID 35326563, 2022). "Evidence of SETD7 as a tumour promoter comes from two studies." (PMID 35326563, 2022). "Collectively, these results suggest that SETD7 may have a tumour-promoting role in HCC by stimulating the cell cycle through E2F-1 stabilisation and possibly also by enhancing migration and metastasis." (PMID 35326563, 2022). "Since both SETD7 and GLI1 mRNA levels were upregulated in A-549 cell line when compared to the non-malignant bronchial epithelial lung cell line BEAS-2B, it is likely that SETD7 activates the SHH signalling in LCa promoting tumour growth and metastasis in vitro and in vivo via GLI3 methylation." (PMID 35326563, 2022). "Since GLI1 mRNA and protein where negatively correlated with SETD7 expression, it is possible that tumour-suppressing effects of SETD7 could be mediated by reducing GLI1 expression." (PMID 35326563, 2022). "Overall, high SETD7-expressing tumours showed higher stromal and lower immune scores." (PMID 36551516, 2022). "Four studies point towards a tumour-promoting role of SETD7." (PMID 35326563, 2022). "Evidence supporting a role for SETD7 as tumour suppressor was presented in six studies." (PMID 35326563, 2022). "Overall, the genetic alteration of SETD7 was not a common occurrence in BC, but a heterogeneous copy number loss was frequent (47%) in basal-like tumours specifically." (PMID 36551516, 2022). "In other word, SETD7 was unveiled as a tumor-promoter in LUAD by the current research." (PMID 33372601, 2020). "Moreover, the tumour metastasis related genes whose levels were substantially affected by SETD7 were consistent with the roles of METTL3 and YTHDF2 in EMT progression." (PMID 32126149, 2020). "SETD7 expression was significantly higher in HCC tumor tissues than in ANLTs." (PMID 27183310, 2016). "In this study, SETD7 is more highly expressed in HCC tumor tissues than in ANLTs." (PMID 27183310, 2016). "IHC assay revealed that SETD7 is significantly higher in HCC tumor tissues than in ANLTs." (PMID 27183310, 2016). "The IHC scores of SETD7 in HCC tumor tissues and ANLTs are indicated in the box plots." (PMID 27183310, 2016). "Considering the higher expression of SETD7 in HCC tumor tissues than in ANLTs, we determined whether SETD7 would affect cell function." (PMID 27183310, 2016). "Furthermore, xenograft models showed that SETD7 promotes ESCC tumor growth in vivo." (PMID 41203594, 2025). "Finally, we ran qPCR to investigate mRNA expression of metastatic and apoptotic genes that could have been affected by Setd7 knocking out or inhibition by CPH in primary tumor." (PMID 39522095, 2024). "Similarly, we found that miR-1298-5p could target SETD7 to affect AKT pathway to inhibit tumor proliferation." (PMID 35501306, 2022). "Thus, in the present study, we examined the expression of SETD7 in HCC tumor tissues and ANLTs." (PMID 27183310, 2016). "Functional analyses revealed that SETD7 promotes ESCC cell proliferation and migration in vitro, while accelerating tumor growth in vivo." (PMID 41203594, 2025).
tumor (continued). "To further investigate how Setd7 KO and its inhibitor CPH regulate metastasis at the molecular level and explore the related biomarkers, we analyzed tumor tissues’ cellular metabolites using LC/MS/MS technology." (PMID 39522095, 2024). "Among these PKMTs, SETD2, SETD7, and EZH2 are relatively well characterized with dominant tumor-suppressive functions." (PMID 38036730, 2023). "SETD7 was needed for GATA-1-induced cell viability in vitro, and for tumour growth and angiogenesis in MDA-MB-231 xenografts." (PMID 35326563, 2022). "Thus, SETD7 could be a marker of chemoresistance for patients with basal-like tumours." (PMID 36551516, 2022). "Therefore, SETD7 could mediate GATA-1 tumour-promoting functions in BC." (PMID 35326563, 2022). "METTL3 also catalyzes m6A modifications in the mRNAs of SETD7 and KLF4, two tumor suppressors that are part of the METTL3/YTHDF2-SETD7/KLF4 m6A axis." (PMID 32765970, 2020). "The accumulated expression of SETD7 and KLF4 upon METTL3 depletion was also discovered in UM‐UC‐3 derived xenograft tumours obtained from nude mice." (PMID 32126149, 2020). "SMYD2, EZH2, and SUV420H2 were up‐regulated and SETD7, PRDM1, PRDM8, PRDM6, and PRDM5 were down‐regulated in tumor." (PMID 30984543, 2019). "It is evident that the mRNA level of SPOP, VDR and SETD7 in CRC tissues is lower than in normal adjacent tissues, indicating the tumor suppressive roles of these genes and the poor differentiation of CRC." (PMID 30171794, 2018). "As expected, SETD7, H3K4me2, CDKN2D, and ZBTB20 are significantly higher in HCC tumor tissues than in ANLTs." (PMID 27183310, 2016). "To determine whether SETD7 regulates ALDH1A3 expression in vivo, we analyzed xenograft tumor tissues using RT-qPCR, Western blotting, and IHC staining." (PMID 41203594, 2025). "In addition, we co-transfected 786-O and CAKI-1 cells with SETD7 siRNAs and TAF7 overexpressing plasmids to assess their potential counteracting effects on tumor cell proliferation and migration." (PMID 38904013, 2024). "Therefore, SETD7-mediated methylation of YY2 at K247 positively regulates YY2-target gene’s transcription, which mediates the inhibitory function of YY2 in cell proliferation and tumour growth, and points to mutations affecting K247 methylation that could be pathologically relevant." (PMID 35326563, 2022). "Two YY2 somatic mutations (K244Q and S246F) near K247 reduced its methylation by SETD7, while the unmethylatable K247R mutant was not as efficient in attenuating cell proliferation and tumour growth." (PMID 35326563, 2022). "A second methylation target site of SETD7 on HIF-1α protein (K391) also destabilises HIF-1α but can be reversed by the lysine-specific histone demethylase 1A (also known as LSD1) to induce VEGFA transcription and tumour angiogenesis." (PMID 35326563, 2022). "Immunohistochemical analysis of 225 primary HCC tumors demonstrated SETD7 overexpression compared to neighboring non-tumorous counterparts and correlation with adverse clinicopathologic features, such as tumor size and histologic grade." (PMID 33050946, 2020). "In the context of tumor, however, we found a significantly negative relationship between SETD7 and KEAP1 both in the TCGA database and in experimental discoveries." (PMID 29212211, 2017). "Furthermore, SETD7 methylation of HIF-1α inhibits angiogenesis and tumor growth." (PMID 39522095, 2024). "In addition, to further evaluate the role of SETD7 in ccRCC metastasis in vivo, we established a tail vein metastasis model by injecting CAKI-1 cells into nude mice and detected the distribution and size of the tumor on the 21th day after injection." (PMID 38904013, 2024).
tumor (continued). "KMT7 (also known as SETD7) was shown to be overexpressed in HCC tumour tissues compared to adjacent non-tumoural liver tissues, and it was shown to be positively correlated with tumour size and poor tumour differentiation leading to poor prognosis in HCC patients." (PMID 36650321, 2023). "Notably, a cohort analysing only ER (ESR1)-negative tumours showed that high-SETD7 was significantly correlated with a poor prognosis." (PMID 36551516, 2022). "Even though one might assume these results suggest that SETD7 could serve as a prognostic marker for luminal tumours in stage 2, this was not confirmed when we pooled stage 2 samples of luminal subtypes from TCGA PanCancer or METABRIC cohorts (not shown)." (PMID 36551516, 2022). "Moreover, knocking out Setd7 reduced lung nodules significantly but could not affect the primary tumor growth, which suggests that the presence of Setd7 in the environment might have a role in regulating tumor cells at the molecular level." (PMID 39522095, 2024). "Interestingly, others showed that K271 on FOXO3 was methylated by SETD7, which decreases FOXO3 protein stability while moderately enhancing FOXO3-dependent activation of pro-apoptotic genes, which may in turn affect FOXO3’s ability to promote tumor suppression." (PMID 35812730, 2022). "Although several studies have revealed that inhibition of SETD7 improved ROS clearance through modulating the KEAP1-NRF2 pathway, these studies failed to explain the relationship between SETD7 and ROS in tumor cells." (PMID 29212211, 2017). "mRNAs and proteins of SETD7 and related genes in HCC tumor samples and paired adjacent non-tumorous liver tissues (ANLTs) (n = 20) or culture cells were determined by quantitative real-time PCR and Western blot." (PMID 27183310, 2016).
infection (7 papers, 2015 to 2024). The state of being infected such as from the introduction of a foreign agent such as serum, vaccine, antigenic substance or organism. "Nevertheless, Setd7 deletion provides resistance to infection even in mice that completely lack an adaptive immune system." (PMID 27598373, 2016). "We infected mice with an IEC-specific deletion of Setd7 (Setd7ΔIEC mice) with T. muris and found that similar to Setd7-/- mice, Setd7ΔIEC mice displayed enhanced resistance to infection, with reduced worm burden at day 14 post-infection." (PMID 27598373, 2016). "Furthermore, in a study using the murine helminth models, it was shown that the gene deletion for SETD7, a histone lysine N-methyltransferase mediating methylation of target genes, has rendered mice resistant to infection by Trichuris muris." (PMID 39795948, 2024). "At day 21 post infection both wild type and knock out mice had fully cleared the infection, indicating that complete loss of Setd7 does not render mice susceptible to T. muris infection." (PMID 27598373, 2016). "Both Hippo and Wnt gene expression programs are induced upon infection and are mediated by SETD7." (PMID 27598373, 2016). "Lack of SETD7 resulted in downregulation of Wnt/β-catenin and susceptibility to infection." (PMID 32616023, 2020). "In contrast, mice deficient in SETD7 (a member of the suppressor of variegation 3-9-Enhancer of zeste-Trithorax domain-containing family of lysine methyltransferases) were not able to reject the infection." (PMID 32616023, 2020). "Thus, IEC-intrinsic expression of SETD7 negatively regulates resistance to infection with T. muris." (PMID 27598373, 2016). "In the absence of SETD7, we found that Wnt target gene expression is reduced while Hippo target gene expression is increased in IECs following infection." (PMID 27598373, 2016). "We find that Setd7-/- mice display increased resistance to infection with the helminth Trichuris muris but not Heligmosomoides polygyrus bakeri." (PMID 27598373, 2016). "Despite the increased immunity to infection in Setd7-/- mice, we did not detect any significant differences in expression of TH1 cell- or TH2 cell-mediated cytokine genes such as Ifng and Il13 in the gut by qPCR." (PMID 27598373, 2016). "Here we show that SETD7 does not affect immune cell responses during infection." (PMID 27598373, 2016).
hematological disease (1 paper, 2021). "Genes highlighted here in, such as PRDM16, PER3, NOM1 BAHCC1, ZNF423, SETD7, RPTOR, and others have been implicated in hematological disease development, progression or clinical outcome." (PMID 34200630, 2021).
metabolic disorders (1 paper, 2015). "In addition, further studies in mouse models to test the effect of SETD7 inhibition would be necessary to evaluate the therapeutic potential of targeting SETD7 in treating various ROS-associated diseases including inflammation, neurodegeneration and metabolic disorders." (PMID 26435321, 2015).
SETD7 also shares sentences with these, for which no sentence is quoted: colorectal cancer (8 papers); glioblastoma (5); leukemia (4); atherosclerosis (3); chronic kidney disease (3); kidney diseases (3); triple-negative breast carcinoma (3); type 2 diabetic (3); Alzheimer disease (2); diabetic kidney disease (2); multiple myeloma (2); Peritoneal Fibrosis (2); prostate tumors (2); renal carcinoma (2); thymoma (2); Ureteral obstruction (2); viral infection (2); acute leukemia (1); acute myeloid leukemia (1); adenocarcinoma (1); Allergy (1); Ataxia (1); ataxia telangiectasia (1); benign tumours (1); chronic obstructive pulmonary disease (1); co-infection (1); complication (1); dementia (1); diffuse large B-cell lymphoma (1); endothelial dysfunction (1).
A further 19 diseases each share a sentence with SETD7 in 1 paper.